MTOR (mechanistic target of rapamycin kinase)
Diseases named in the same sentence as MTOR in open-access papers (continued):
Sharing a sentence is not in itself a finding about the gene and the disease.
liver diseases (continued). "However, insufficient evidence is available to prove that the therapeutic and prophylactic administration of EZP prevents hepatic diseases by inhibiting hepatic apoptosis via TSC/mTOR signaling pathway." (PMID 28638431, 2017). "Therapeutic intervention targeting mTOR could be a promising strategy for patients with portal hypertension and splenomegaly." (PMID 26734934, 2016). "The AKT/mTOR signaling pathway played an important role in the early phase of cirrhotic portal hypertension in rats, which could be a potential target for therapeutic intervention in the early phase of such pathophysiological progress." (PMID 24404143, 2014). "However, there is still little known about the specific role of the AKT/mTOR signaling pathway in the early pathophysiologic progress of cirrhotic portal hypertension." (PMID 24404143, 2014). "However, comprehensive and in-depth researches on the AKT/mTOR signaling pathway in cirrhotic portal hypertension have rarely been reported, especially ones on the early phase of this disease." (PMID 24404143, 2014). "Taken these results together, we firstly demonstrated that AKT/mTOR signaling pathway was significantly overactivated and might be involved in the early pathogenesis of cirrhotic portal hypertensive rats." (PMID 24404143, 2014). "However, it is unclear whether Pue can inhibit mTOR signaling to prevent excessive apoptosis in the treatment of hepatic diseases." (PMID 30405406, 2018). "Indeed, strategies aimed to restore PTEN expression/activity with inhibition of IKK/NF-κB and mTOR signaling in injured hepatocytes might counteract hepatic IR, steatohepatitis and potentially more serious liver diseases for prolonged survival." (PMID 25645159, 2015). "With recent structural elucidation of NTCP, new insights into the interaction of NTCP with mTOR inhibitors can be investigated and the underlying mechanisms of NTCP transport and inhibition could be leveraged to develop novel inhibitors for the treatment of liver diseases." (PMID 37033614, 2023). "More importantly, signaling pathways such as Nrf2, NF-κB, PI3K/Akt/mTOR, NLRP3, Wnt/β-catenin, TGF-β1/Smad3, AMPK/SREBP, PPARα/γ, MAPKs, and Caspases are identified as key targets through which API exerts its beneficial effects in various liver diseases." (PMID 39749193, 2024). "The protective effect of MOE on liver diseases is probably due to the presence of quercetin, which plays a pivotal role in the prevention of liver inflammation through inhibiting NF-kB/TLR/NLRP3, inactivation of autophagy-mediated cell apoptosis (under ER stress) through the mTOR pathway." (PMID 41516140, 2025).
prostate tumors (40 papers, 2011 to 2026). "The authors showed that about a quarter of localized prostate tumors displayed activating mutations of the PI3K/Akt/mTOR and MAPK signaling pathways." (PMID 31885728, 2019). "The importance of both ACC1 and mTOR in enabling PCa cells to meet their energy demands is increasingly well recognised; indeed, both of these factors are key mediators of de novo lipogenesis, high levels of which are a hallmark of prostate tumours." (PMID 34382934, 2021). "Moreover, loss-of-function of the tumor suppressor gene PTEN, which results in constitutive activation of AKT and upregulation of mTOR activity, has been implicated in the etiology of numerous human cancers including more than 50% of advanced prostate tumors." (PMID 22614157, 2012). "Exogenous IL1A reinstated the capacity of senescent mouse fibroblasts to enhance prostate tumor growth through MTOR inhibition." (PMID 40612864, 2025). "Compared with Pten-null animals with intact Cdk12, these double knockout mice demonstrated improved survival and markedly reduced prostate tumor size, as well as impaired mTOR signaling." (PMID 39368479, 2024). "Suppression of the AMPK/mTOR pathway decreases autophagic flux and reduces the number of autophagosomes, resulting in the evolution of docetaxel-acquired resistance in prostate tumour cells." (PMID 37801481, 2023). "Other significant pathways found to be upregulated in prostate tumors are the phosphatidylinositol-3-kinase (PI3K)/Akt/mammalian target of rapamycin (mTOR), Ras/MAPK, DNA repair, and receptor tyrosine kinase pathways." (PMID 36937425, 2023). "Eventually, the inhibition of mTOR signalling induced prostate tumour dormancy and contributed to chemoresistance in vitro and in vivo." (PMID 36307871, 2022). "In vivo use of A-443654 was previously reported in mice, and when delivered by subcutaneous injection, it reached plasma and tissue concentrations above 0.5 μM and effectively inhibited mTOR phosphorylation in human prostate tumor xenografts." (PMID 34520759, 2021). "To date, a number of plant-derived natural products have been shown to have favorable activities against prostatic neoplasms through the down-regulation of the mTOR-signaling pathway." (PMID 34452154, 2021). "The variety of actions of mTOR in the modulation of intestinal inflammatory events underscores a novel receptor targeting for the management of prostatic neoplasms." (PMID 34452154, 2021). "Many studies reported that the mTOR-signaling pathway was a target of these synthetic products against prostatic neoplasms." (PMID 34452154, 2021). "Clinical studies should be further conducted to clarify the potential therapeutic role of mTOR in prostatic neoplasms patients." (PMID 34452154, 2021). "Thereby, we present data that confirm mTOR is a major and novel regulator of inflammation in the treatment of prostatic neoplasms." (PMID 34452154, 2021). "In line with this, recent reports showed that targeting the PI3K/AKT/mTOR pathway resulted in a compensatory increase in the RAS/RAF/MEK/MAPK pathway in primary prostate tumour samples, indicating strong crosstalk between those pathways as postulated earlier." (PMID 32102484, 2020). "Intriguingly, these therapy-resistant prostate tumors exhibit an increased reliance on mTOR-dependent transcriptional activation of glycolytic and oxidative phosphorylation genes to stimulate their metabolism." (PMID 32532005, 2020). "Co-treatment induced a robust AMPK activation and Akt/mTOR axe inhibition in the PC3 prostate tumors." (PMID 30899201, 2019). "Targeting PI3K/AKT/mTOR and MAPK pathways by combined PD325901 (MEK inhibitor) and rapamycin (mTOR inhibitor) treatment reduced prostate tumor burden of Nkx3.1+/−Pten+/− mice, particularly following castration." (PMID 25595909, 2015). "In accordance with other reports of mTOR inhibition, ridaforolimus treatment of the prostate tumor lines increased expression of PSA, despite its inhibitory effects on cell growth." (PMID 22614157, 2012).
prostate tumors (continued). "PTEN loss in prostate tumors is primarily associated with cancer-cell proliferation and survival through the activation of the phosphoinositide 3-kinase (PI3K)-protein kinase B (AKT)-mechanistic target of rapamycin (mTOR) (PI3K-AKT-mTOR) signaling pathway." (PMID 41247227, 2025). "In addition to the small-molecule mTOR inhibitors, there are evidence that several natural agents are able to target the PI3K/Akt/mTOR pathway in prostatic neoplasms." (PMID 34452154, 2021). "This increased dependency on nuclear mTOR may create a metabolic vulnerability that can be therapeutically targeted to treat prostate tumors resistant to standard androgen ablation therapy." (PMID 32532005, 2020). "In addition, it promotes the autophagic degradation of EGFR in non-small cell lung cancer (NSCLC), inhibits growth and angiogenesis in prostate tumors by suppressing the protein kinase B (Akt)/mammalian target of rapamycin (mTOR)/P70S6K pathway." (PMID 32116702, 2020). "Moreover, PTEN negatively regulated activity of the PI3K/Akt/mTOR pathway, which played a prominent role in prostate tumor development." (PMID 27634882, 2016). "In addition to the mouse study these authors were able to show, using human patient tissue microarrays, that aberrant activation of some of the Ras/PI3K/PTEN/Akt/mTOR pathway components (Akt, mTOR, p70S6K) are frequent in progressed human prostate tumors." (PMID 21422497, 2011). "The combination of an mTOR and autophagy inhibitor may be important for clinical efficacy, as a study in prostate tumour xenograft models found that the combination of the mTOR inhibitor AZD5363 and chloroquine significantly reduced tumour volume, while either drug alone did not." (PMID 27687594, 2016). "In prostate tumor cells, the current research results stated that knocking down miR-124-3p led to a considerable reduction in AKT and mTOR levels, whereas overexpressing miR-124-3p had the opposite effect." (PMID 36884182, 2023). "Similarly, prostate tumour cells increased their expression of TBK1 to interact with and inhibit mammalian/mechanistic target of rapamycin (mTOR) when binding to osteoblasts." (PMID 36307871, 2022). "Furthermore, increased nuclear mTOR in prostate tumors promotes tumorigenesis even in the absence of functional AR which correlates with worse patient survival." (PMID 32532005, 2020).
B-cell lymphoma (39 papers, 2010 to 2026). "Hence, oncogenic RRAGC mutation strongly enhances mTOR activation and accelerates B cell lymphoma cell proliferation." (PMID 37749558, 2023). "This suggests that patients with treatment-resistant MYC-translocated NH B-cell lymphomas might be susceptible to a combination of CB-839 and mTOR inhibitor." (PMID 30564554, 2018). "The data provide a rational basis for integrating CD79B-directed ADCs with mTOR or CDK4/6 inhibitors to prevent or overcome treatment resistance of aggressive B cell lymphomas." (PMID 41668618, 2026). "This has already been described regarding TNFRSF8, which has subtype-specific effects on the growth of T-cell and B-cell lymphoma cell lines, as well as mTOR activity, which is restricted to ABC DLBCL-s in most of the cases." (PMID 38460675, 2024). "The biological role of mTOR in B-cell lymphomas, anti-neoplastic agents that target the mTOR pathway, and the respective therapeutic context have also been reviewed." (PMID 39518937, 2024). "Combining low‐dose statin treatment with the mTOR inhibitor rapamycin produced a synergistic effect, significantly inhibiting B‐cell lymphoma proliferation, cell cycle progression, and lipid raft formation." (PMID 39501600, 2024). "The activation of the PI3-K/Akt/mTOR signaling pathway is well established in various types of B cell NHLs, such as DLBCL, MCL, chronic lymphocytic leukemia (CLL) and hairy cell leukemia (HCL)." (PMID 37762410, 2023). "That is why, in PTEN mutant B-cell lymphoma, post mTOR inhibitor treatment, a high level of autophagy induction is observed compared to wt PTEN-harboring KSHV cells." (PMID 37602330, 2023). "For R/R aggressive B cell lymphomas, the efficacy of mTOR inhibitors was very modest with increased toxicity." (PMID 37762410, 2023). "PDE4B, an isoform of PDE4, is highly expressed in refractory DLBCL patients and the anticancer effect of PDE4 inhibitors has been confirmed in B-cell lymphoma in vitro and in vivo, associated with repression of the SYK/AKT/mTOR pathway." (PMID 34833935, 2021). "Mechanistically, PRDM15 regulates a transcriptional program that sustains the activity of the PI3K/AKT/mTOR pathway and glycolysis in B-cell lymphomas." (PMID 32665551, 2020). "The PI3k signaling also activates the Akt and mTor pathways which also are involved in B cell proliferation and, noteworthy, their activation has been observed in B cell lymphomas." (PMID 31480511, 2019). "Secondly, can we predict the response of NH B-cell lymphoma patients to rapalog by detecting mTOR targets in tumors?" (PMID 30564554, 2018). "Constitutive signaling of PI3K/Akt/mTOR plays a prominent role in malignant transformation and progression of B-cell non-Hodgkin lymphomas (B-NHL) underscoring the need for PI3K targeted therapies." (PMID 29515122, 2018). "In support of these findings, it has been reported that certain dual targeted PI3K/mTOR inhibitors efficiently killed primary c-Myc-driven B-cell lymphomas and human cell lines bearing IG-c-Myc translocations." (PMID 27769069, 2016). "The purpose of this paper is to summarize the existing knowledge about mTOR inhibitors and their use in the treatment of B-cell lymphomas." (PMID 21822434, 2012). "Many groups have documented high basal levels of Akt and mTOR activation in B cell leukemias, B cell lymphomas, and multiple myeloma (MM) cells." (PMID 22888331, 2012). "Key pathways implicated in the pathogenesis of canine lymphoma include the nuclear factor kappa B (NF-κB) pathway, which is often activated in B-cell lymphomas, and the mechanistic target of rapamycin (mTOR) pathway, which is frequently altered in T-cell lymphomas." (PMID 40002191, 2025).
B-cell lymphoma (continued). "Consequently, the combined application of statin with an mTOR inhibitor rapamycin, even at a low dose, can strongly suppress B‐cell lymphoma proliferation." (PMID 39501600, 2024). "The PI3K/AKT/mTOR signaling pathway, for instance, has been shown to participate in the cell pro-survival and metabolic reprogramming involving fatty acid metabolism, glycolysis, and tricarboxylic acid cycle in B-cell lymphoma." (PMID 36982568, 2023). "We further checked the importance of PTEN status in determining the mTOR inhibitor resistance by comparing the effect of mTOR inhibitors against PTEN-deleted B-cell lymphoma cells (BJAB) and checked the ability of mTOR inhibitors as the modulator of drug resistance in such PTEN-deleted condition." (PMID 37602330, 2023). "Thus, this review will focus to the role of mTOR inhibitors in B cell non-Hodgkin lymphomas with an emphasis on the role of temsirolimus in MCL." (PMID 37762410, 2023). "In the current experiments, we tried to understand whether the constitutive endogenous PTEN expression inside KSHV-infected B-cell lymphoma puts any differential mTOR inhibitor’s sensitivity." (PMID 37602330, 2023). "TECs releasing IL-6, promoting suppression of PI3K/AKT/mTOR pathway in B-cell lymphoma." (PMID 34095111, 2021). "The PI3K/Akt/mTOR pathway is known to be deregulated especially in NHL (a primarily B-cell lymphoma in humans), and the response of both this dog and two of our T-cell lymphoma dogs (a much more rare condition in humans) to the high dose of the inhibitor is promising." (PMID 23593398, 2013). "The results of this current study demonstrate that the in vivo apoptotic effects of rapalog and active site mTOR inhibitors are caused by the downregulation of VEGF protein expression and the subsequent inhibition of angiogenesis in a B-cell lymphoma xenograft." (PMID 23533410, 2013). "Herein we aim to review the results of trials with mTOR inhibitors in B-cell lymphomas." (PMID 21822434, 2012). "Furthermore, inhibitors of mTOR were less successful in clinical studies in the treatment of B cell lymphomas than expected based on pre-clinical experiments, suggesting the need for multi-target approaches that include inhibitors of mTOR in conjunction with HIF-1α." (PMID 38612754, 2024). "In RAJI cells (Burkitt lymphoma) and SLVL cells (splenic B cell lymphoma), mutations of DNA-binding protein inhibitor ID-3 (ID3), transcription factor 3 (TCF3), and neurogenic locus notch homolog protein 2 (NOTCH2) increase phosphorylation of proteins in Akt/mTOR pathway." (PMID 33490663, 2021). "This review aims to demonstrate how the BCR, specific signaling pathways like PI3K/AKT/mTOR, NF-kB, and JAK/STAT are diverse in common types of B-cell lymphoma." (PMID 39563886, 2024). "A similar organization, with a gradient of BCR activity and a subgroup with BCR-independent mTOR activity, appeared in MCL, a related B cell lymphoma." (PMID 29227286, 2018). "Additionally, the PI3K/Akt/mTOR pathway has been reported to play a central role in the activity of a variety of targeted therapeutic agents under pre-clinical investigation in aggressive B-cell NHL, in many cases through alterations in BCL-2 family protein expression." (PMID 29774105, 2018). "Altogether, these findings suggest that trisomy 12 drives B cell lymphoma by modulating PI3K, MEK/ERK, and mTOR pathways and amplifying BCR signaling." (PMID 29227286, 2018). "With regard to B-cell lymphomas, both of them have been tried in MCL and FL cell lines and were shown to downregulate Akt and/or mTOR activity." (PMID 21822434, 2012). "Everolimus is an oral mTOR inhibitor, which has been evaluated in B cell lymphomas but has not been approved by the US or European regulatory authorities." (PMID 37762410, 2023). "In canine B-cell lymphoma and specifically in cDLBCL, the mechanism might be similar, since PI3K/AKT/mTOR pathway is frequently deregulated." (PMID 34209830, 2021).
B-cell lymphoma (continued). "Overall, our data indicate that AGN/decursin can efficiently block Myc expression by downregulating PI3K/AKT/mTOR and MAPK signaling pathways, critical downstream mediators of BCR, and exert synergistic effects against B-cell lymphoma when combined with Myc inhibitors." (PMID 30002430, 2018). "Similar to the mTOR pathway, miR‐155 is an evolutionarily ancient miRNA that not only regulates the immune system, with significant roles in bacterial infection, but also has been used as a biomarker for disease progression in B‐cell lymphoma." (PMID 34913612, 2022). "Furthermore, a dual PI3K/mTOR inhibitor has recently been reported to have synergistic effect with 2-DG on cell survival in two cell lines of primary effusion lymphoma (PEL), a rare subtype of B-cell NHL." (PMID 28724379, 2017). "It is very interesting that the Eμ-myc model of B-cell lymphoma, one of the earliest transgenic mice ever developed to still be widely used today, also showed a requirement for PI3K, but not mTOR or ERK, activity in mitogen-induced B-cell growth." (PMID 20433747, 2010).